IGF1R (insulin like growth factor 1 receptor)
Diseases named in the same sentence as IGF1R in open-access papers (continued):
Sharing a sentence is not in itself a finding about the gene and the disease.
metastatic disease (29 papers, 2009 to 2025). "In ES, IGF-1R signaling is constitutively active and has been implicated in the tumorigenesis, growth, proliferation, and the development of metastatic disease." (PMID 32477459, 2020). "In addition, low IGF1-R expression in this group was linked to a higher likelihood of metastatic disease." (PMID 41009559, 2025). "In metastatic tumors, bone metastasis-prone IGF-1R levels were much higher than those of tumors prone to metastasis to other organs." (PMID 38342894, 2024). "In UM, an increased insulin-like growth factor 1 receptor (IGF-1R) expression was detected in liver metastasis and was correlated with mortality in the context of metastatic disease." (PMID 37629523, 2023). "IGF-1R overexpression has been described in OS and has been correlated with metastatic disease and poor overall survival, indicating that IGF-1R is a therapeutic target of interest in OS." (PMID 33567616, 2021). "The reduction in the frequency of IGF1R‐expressing CTCs upon the transition from early to metastatic disease state implies a potential role for IGF1R in maintaining a less aggressive disease phenotype." (PMID 28766847, 2018). "100% of CTC(+) patients with early disease, compared to 79% of those with metastatic disease, harbored IGF1R(+) CTCs (P = 0.007)." (PMID 28766847, 2018). "IGF1R(+) CTCs were more frequently observed in early disease than in metastatic disease (86% vs 68% of CTCs, P = 0.04) stage, whereas IGF1R(−) CTCs were more common in metastatic than in early disease (32% vs 14% of CTCs, P = 0.002)." (PMID 28766847, 2018). "IGF1R and E‐cadherin are coexpressed at the single CTC level, and the transition from early to metastatic disease stage is associated with a reduction in the expression of both molecules." (PMID 28766847, 2018). "A IGF-1R QS lower than 0.4–0.5 correlated with metastatic disease at diagnosis (AUC 0.715 ± 0.065; p = 0.003)." (PMID 29213282, 2017). "Receiver-operating-characteristic curves were used to determine the best cut-off ranges below which IGF-1R QS correlated with metastatic disease at diagnosis." (PMID 29213282, 2017). "Cell lines and metastatic tumor cells isolated from patients expressed IGF1R, and insulin-like growth factor-1 (IGF-1) activated the PI3-kinase/Akt and Ras/Raf/MAP-kinase pathways." (PMID 27437872, 2016). "A limited number of sections of metastatic tumor from the following time points were available 1) before IGF1R antibody therapy; and 2) from the resistant recurrence that emerged during IGF1R antibody therapy." (PMID 21494688, 2011). "IGF-1R was also more upregulated in metastatic tumors than in non-metastatic tumors." (PMID 38342894, 2024). "In summary, there is substantial evidence regarding the critical role of IGF-1/IGF-1R signaling in the progression of PCa, with studies reporting correlations of IGF-1/IGF-1R with tumor cell proliferation, Gleason score, metastatic disease progression, and clinical outcomes." (PMID 36831629, 2023). "We aimed to determine how IGF1R deficiency acts in the lung tumor microenvironment (TME) conditioning metastatic tumor implantation and progression, by generating LLC models using heterotopic transplantation or pulmonary metastasis in the context of IGF1R deficiency." (PMID 35688943, 2022). "Similarly, in paired samples of patients with early disease that progressed to metastatic disease, the proportion of IGF1R(+)/E‐cadherin(+) CTCs was reduced and IGF1R(−)/E‐cadherin(−) CTCs were increased in the metastatic stage compared to early disease stage." (PMID 28766847, 2018). "Moreover, immunohistochemical studies of USC tumors revealed high protein expression of BRCA1 and IGF1R in primary and metastatic tumors." (PMID 29922232, 2018). "Interestingly, here we report that IGF1R immunostaining is more frequently observed among CTCs in early compared to metastatic disease." (PMID 28766847, 2018).
metastatic disease (continued). "RNA-Seq data further revealed that the downstream target of the IGF2BP2-IGF2 axis, IGF1R, was significantly increased in metastatic tissues, whereas the inhibitor of the PI3K-AKT pathway PTEN was decreased in both primary and metastatic tumor tissue." (PMID 37248468, 2023). "On the other hand, p-IGF1R and p-ERK1/2, assessed by immunohistochemistry in metastatic tumors, demonstrated smaller stained areas in LLC-challenged CreERT2 mice." (PMID 35688943, 2022). "We found seven DEGs (CCND1, EGFR, ENTPD5, HOXA10, IGF1R, MYC, and SNAI2) related to metastatic disease." (PMID 35806108, 2022). "High IGF1R expression (grades III–IV) was recorded in 42.8% of the primary tumors and 77.8% of the metastatic tumors." (PMID 24904527, 2014). "There were no CTCs expressing only IGF1R or E‐cadherin either in the early or in metastatic disease stage." (PMID 28766847, 2018). "Patients with tumors with low or absent membranous IGF-1R expression (0 or 1+) presented more frequently with locally advanced or metastatic disease." (PMID 25680198, 2015). "Case OVA_048 also presented with a single actionable deleted NFKBIA gene in its metastatic tumour, but also had a single actionable IGF1R amplification in its primary tumour, whereas no actionable genes were shared between the primary HGSOC and metastatic tumours." (PMID 32099096, 2020).
small cell lung carcinoma (29 papers, 2004 to 2025). Small cell lung cancer (SCLC) is a highly aggressive malignant neoplasm, accounting for 10-15% of lung cancer cases, characterized byrapid growth, and early metastasis. "Inhibition of IGF1R (Insulin-like growth factor receptor 1) has been found to be efficacious together with etoposide and cisplatin in small-cell lung cancer and further clinical trials are undergoing with other drugs and cancer types." (PMID 31523390, 2019). "The use of monoclonal antibodies against IGF-1R accompanying cisplatin improved inhibitory efficacy in small cell lung cancer in vivo and in vitro in nude mice bearing the tumors." (PMID 30241323, 2018). "Combination therapy of metformin with anti-IGF1R mAb Figitumumab or an epidermal growth factor receptor (EGFR) tyrosine kinase inhibitor produces a synergistic effect in small cell lung cancer (SCLC) and NSCLC." (PMID 29254182, 2017). "CircVAPA could activate the phosphoinositide 3-kinase (PI3K)/protein kinase B (AKT) signaling pathway by modulating the miR-377-3p and miR-494-3p/insulin-like growth factor 1 receptor (IGF1R) axis to accelerate small cell lung cancer progression." (PMID 37298501, 2023). "Hence, we confirmed that NNK induced IGF-1R phosphorylation by utilizing HCC-15 non-small cell lung cancer cells that lack IR expression." (PMID 27708216, 2016). "In small-cell lung cancer (SCLC) cell lines and clinical tissues, circVAPA was overexpressed to raise the IGF1R expression via sequestering miR-377-3p and miR-494-3p." (PMID 39524849, 2024). "In addition, the SCLC (small cell lung carcinoma) patients demonstrated higher mRNA levels of IGF1R (p = 0.010) and MAPK15 (p = 0.040) than the other BP-NEN groups." (PMID 33138224, 2020). "Deregulation of IGF signaling has been described in several cancer types, including both non-small cell lung cancer (NSCLC) and small cell lung cancer (SCLC), and high expression of IGF-1R in NSCLC has been reported." (PMID 25944691, 2015). "Several inhibitors of IGF-1R, including monoclonal antibodies and small molecule tyrosine kinase inhibitors, have entered clinical development for the treatment of solid tumors, including non-small cell lung cancer (NSCLC), small cell lung cancer (SCLC), and ovarian carcinoma (OC)." (PMID 29786660, 2018). "Further, not all NSCLC erlotinib-resistance mechanisms reported in the literature were exhibited by the PERCs; we found no compelling evidence of transformation to small cell lung cancer, epithelial-to-mesenchymal transition or activation of IGF1R, AXL or NFK-B." (PMID 26891683, 2016).
Alzheimer disease (28 papers, 2010 to 2026). A progressive, neurodegenerative disease characterized by loss of function and death of nerve cells in several areas of the brain leading to loss of cognitive function such as memory and language. "Additionally, increases in brain IGF-1R and compromised insulin receptor signaling have been associated with neurodegenerative diseases such as Alzheimer’s disease." (PMID 22844398, 2012). "Beyond their apparent involvement in cancer pathology, the anti-inflammatory activity of IGF-1 in mouse models of Alzheimer's disease, or the proliferation of intestinal cells depends also on IGF-1R nuclear signaling." (PMID 39638246, 2024). "In fact, heightened activity within this pathway is an early feature of Alzheimer’s disease (AD), likely due to increased activation by insulin like growth factor (IGF-1R) and insulin receptors (IR)." (PMID 39763909, 2024). "Neurons in Alzheimer’s disease that lack IGF1R exhibited a reduced accumulation of amyloid beta-containing autophagic vacuoles while the amyloid beta levels in plasma increased." (PMID 36771351, 2023). "It has been shown that increased IGF1R signaling was apparent in postmortem brains of Alzheimer’s disease (AD) patients, suggesting that a long-term increase in activity is associated with the progression of AD neuropathology." (PMID 36776414, 2022). "Our computational approach pointed out 54 candidate drugs, mainly targeting MAPK and IGF1R signaling pathways, which could be further evaluated for their potential as Alzheimer’s disease therapy." (PMID 36604493, 2023). "Previous studies have shown that neuroinflammation could be attenuated by IGF1R inhibition in an experimental autoimmune encephalomyelitis model of multiple sclerosis or Alzheimer’s disease." (PMID 37717026, 2023). "Thus, we can study how a single variant may down-regulate IGF1R signaling in a more precise pathway-specific manner to provide a protective environment to delay brain aging and prevent the development of neurological conditions such as Alzheimer’s disease (AD)." (PMID 36776414, 2022). "Importantly, Igf1r haploinsufficiency was also able to correct the synaptic deficits of APP695/swe mice, a model of Alzheimer’s disease." (PMID 20409077, 2010). "Finally, we show that haploinsufficiency of Igf1r is also able to correct the synaptic deficits of APP695/swe mice, a commonly used model of Alzheimer’s disease (AD)." (PMID 20409077, 2010). "Our finding of IGF-1R upregulation in NEVs is promising because several post-mortem and epidemiological studies support the idea that upregulation of IGF signaling may protect against Alzheimer’s disease (AD)." (PMID 36359767, 2022).
esophageal cancer (23 papers, 2014 to 2025). A primary or metastatic malignant neoplasm involving the esophagus. "Both the epidermal growth factor receptor (EGFR) and insulin-like growth factor 1 receptor (IGF-1R) have been implicated in the development of cancers, and the increased expression of both receptors has been observed in esophageal cancer." (PMID 36142299, 2022). "The insulin growth factor-1 (IGF1) and IGF1 receptor (IGF1R) signaling pathway, implicated in esophageal cancer growth and progression, has been shown to play pivotal roles in cell growth, differentiation, survival, transformation and metastasis." (PMID 26317790, 2015). "Analysis of public datasets of oesophageal cancer RNA expression revealed that IGF1R RNA was elevated in tumours compared to normal tissue." (PMID 40615716, 2025). "IGF-1R/IR phosphorylation was noticed in a wide range of esophageal cancer cell lines under normal growth conditions." (PMID 39335147, 2024). "Here we examined the utility of the small molecule CDK inhibitor flavopiridol and the insulin-like growth factor 1 receptor/insulin receptor (IGF-1R/IR) targeted agent BMS-754807 in the treatment of esophageal cancer with elevated expression of c-Myc." (PMID 34621175, 2021). "We previously demonstrated the pivotal role played by IGF1R signaling in the onset of esophageal cancer in normo-insulinemic and hyperinsulinemic surgically-induced EAC mice." (PMID 34684639, 2021). "The pivotal role of IGF1R signaling in esophageal cancer onset has been exhaustively studied in our surgically induced esophageal adenocarcinoma mouse model." (PMID 34684639, 2021). "In esophageal carcinoma, miR-375 inhibits tumor growth and metastasis through the inhibition of IGF1R." (PMID 30744636, 2019). "Previous studies in esophagus carcinoma cells showed that miR-375 has a tumor suppressor effect by inhibiting IGF1R." (PMID 25110710, 2014). "Tang and colleagues demonstrated the antiproliferative activity of biguanide also in esophageal cancer cells, mediated partly by the suppressed expression of the insulin-like growth factor 1 receptor (IGF-1R) and its downstream targets PI3K, AKT, mTOR, p70S65, and PKM2." (PMID 38610965, 2024). "Specifically, a moderately elevated IGF1R protein abundance was found in early-stage oesophageal cancer (EOC, i.e., OSCC limited to the mucosa or superficial submucosa) tissues compared to adjacent normal tissues, which could provide implications for early diagnosis and treatment." (PMID 36978187, 2023). "Concurrently, some reports also confirmed the high expression of IGF-1R in ESCC and the promotion of proliferation and drug resistance of IGF-1 in esophageal cancer cells." (PMID 38413558, 2024). "Our previous studies found that IGF-1R was also highly expressed in esophageal cancer, and the bispecific fusion protein targeting EGFR and IGF-1R that we constructed had very significant inhibitory activity against esophageal cancer in vitro and in vivo." (PMID 36142299, 2022). "Increased expression of IGF1R, IGFBP3, IGFBP4, IGFBP7, and IGFBP8 was reported in human esophageal cancer, while the expression of IGFBP2 and IGFBP6 was reduced." (PMID 32041673, 2020). "Interestingly, previous studies have shown that resistance to the IGF-1R inhibitor NVP-AEW541 may be driven by its inability to inhibit RAS/RAF/ERK activity in colon, biliary tract and esophageal cancer." (PMID 26317790, 2015). "In this study, we have targeted the type I insulin-like growth factor receptor 1R/IR (IGF-1R) with the small molecule inhibitor BMS-754807 in high c-Myc expressing OE19 esophageal cancer cells, as OE19 showed very strong expression of IGF-1R (data not shown)." (PMID 34621175, 2021).
lymphoma (23 papers, 2010 to 2024). A malignant (clonal) proliferation of B- lymphocytes or T- lymphocytes which involves the lymph nodes, bone marrow and/or extranodal sites. "In the present study, the rs2229765 IGF1R variant has been shown to increase susceptibility for seropositive primary SS and primary SS-related lymphoma." (PMID 34501407, 2021). "Meanwhile, many studies have shown the expression of IGF1R and cMET in lymphomas, which regulate tumor growth and promote malignant transformation 22-24." (PMID 34539876, 2021). "For example, several genes previously identified in other types of lymphomas, such as NOTCH1, POU2F2, CXCR4, and IGF1R, were affected by mutations." (PMID 28152507, 2017). "In this context, we report a novel association of the A/A genotype of the IGF1R gene variant rs2229765 with seropositive SS irrespective of lymphoma status." (PMID 34501407, 2021). "Combination therapies based upon vorinostat and 3-deazaneplanocin resulted in lymphoma growth suppression in vitro and in vivo and restored miR-29 expression, thus leading to inhibition of the lymphoma-associated miR-29 targets, CDK6 and IGF1R." (PMID 25968566, 2015). "In male mice, the only lesions showing any evidence of a difference in incidence were the 36% decrease in all fatal tumors and the 47% decrease in fatal lymphoma in Igf1r+/− mice compared to WT mice; however, these differences do not attain significance when corrected for multiple comparisons." (PMID 22132081, 2011). "Decreased trophic signals in salivary gland epithelial cells due to dampened IGF1R mRNA and protein expression in salivary gland tissues could be related to increased apoptosis and, subsequently, to the activation of inflammasome pathways in the setting of primary SS and SS-related lymphoma." (PMID 34501407, 2021). "In lymphoma cells, PRDM15 regulates the transcription of key genes involved in two major metabolic axes required for tumor cell survival: PI3K/AKT/mTOR signaling (InsR and Igf1R) and glycolysis (e.g Pkm, Pfkp, Eno3)." (PMID 32665551, 2020). "None of the 6 normal lymph node and spleen samples or 42 lymphoma samples expressed detectable levels of MPL, ERBB2, or IGF1R mRNA." (PMID 21318160, 2010). "The insulin receptor IGF-1R inhibitor BMS536924 was the only drug with a confirmed specific activity against Ba/F3 overexpressing BTKE41K-C481S over a large range of doses, but this was not confirmed in the lymphoma cell line TMD8." (PMID 32272741, 2020).
thyroid cancer (23 papers, 2012 to 2026). "IGF1 is mainly produced locally in either a paracrine or autocrine manner and although it is present both in normal and in thyroid cancer tissues, IGF1 and its receptor IGF-1R are found to be overexpressed in thyroid cancer cell lines." (PMID 39199391, 2024). "We evaluated mRNA expression of IGFBP4, IGF1 and IGF1R in thyroid cancers, adenomas and hyperplastic nodules in comparison with their benign counterparts without observing any statistically significant differences." (PMID 34350538, 2022). "Although IGF-1 and IGF-1R are both expressed in normal thyroid tissue and thyroid cancer tissue, compared with normal tissue, IGF-1 and IGF-1R are overexpressed in TCs." (PMID 33815885, 2021). "Some reports show that IGF-1R tumor expression is an aggressive clinical feature and persistent despite thyroid cancer treatment." (PMID 25329702, 2014). "Inhibition of IGF1R can decrease the responsiveness of thyroid cancer cells to growth factors." (PMID 32760219, 2020). "Additionally, we have identified six loci suggestively associated with thyroid volume, of which two, IGF1R and FAM129A, play a role in apoptosis, thyroid morphogenesis and thyroid carcinomas, respectively." (PMID 32019955, 2020). "In thyroid cancer, the fusion of THADA gene with LOC389473 gene leads to abnormal IGF2BPs expression, activating the IGF1R signaling pathway, and promoting the proliferation and invasion of cancer cells." (PMID 40088376, 2025). "Overexpression of IGF-1, IGF-1R, IGF-2 and insulin receptor (IR) can be seen in the early stage of thyroid cancer." (PMID 35711846, 2022). "Overexpression of IGF2BP3 mRNA and protein increases IGF2 translation and IGF1 receptor (IGF1R) signaling through PI3K and MAPK cascade reaction and promotes proliferation, invasion, and transformation of thyroid cancer cells." (PMID 33796449, 2021). "In the context of thyroid cancer, unfortunately, targeting IGF-1R has not been as successful in clinical trials, with some reporting high toxicity and low efficacy." (PMID 40071065, 2025). "Further studies showed that NG2 was involved in maintaining the activities of multiple RTKs, such as EGFR, FGFR, HER2, IGF-1R, VEGFR and PDGFR, suggesting that these RTKs and their downstream signaling pathways may contribute to the resistance of BRAF-mutant thyroid cancer cells to BRAF inhibitor." (PMID 38795180, 2024). "Sorafenib inhibited phosphorylation of VEGFRs and PDGFRs receptors, but did not affect phosphorylation of insulin receptors, IGF1R and the EGF family of receptors in thyroid carcinoma cells." (PMID 25879531, 2015).